CD4 (CD4 molecule)
Diseases named in the same sentence as CD4 in open-access papers (continued):
Sharing a sentence is not in itself a finding about the gene and the disease.
AIDS (continued). "We aimed to compare the effect of DTG- or EFV-based regimens on early mortality rates, frequency of adverse events, CD4 changes from baseline, and treatment changes/discontinuation in patients with advanced AIDS (WHO classification stage 4 and baseline CD4 cell count below 50 cells/mm3)." (PMID 38482527, 2024). "The EuResist Database was established in 2006, to collect, in an anonymized form, data on demographic and clinical characteristics of PLWH, such as antiretroviral therapies, reasons for changing therapy, treatment responses, CD4+ cell counts, AIDS-defining events, and viral co-infections." (PMID 38775719, 2024). "Analysis of all variables with significant differences at baseline showed that those associated with T2DM were age, BMI, heterosexual transmission, time in education, HCV coinfection, non–AIDS-related cardiovascular events, CD4 lymphocyte count, and AIDS stage." (PMID 38560607, 2024). "Of note, MCM 38141 was the only animal temporarily treated with daily combination anti-retroviral therapy (ART) due to severe blood CD4+ T cell depletion and concern that an SIV/AIDS-associated complication unrelated to CyLCV would develop and lead to premature euthanasia." (PMID 39527641, 2024). "The study participants were recruited before the “test and treat era” (2004–2009) and did not qualify for treatment according to the Botswana National HIV guidelines at that time which required PWH to have a certain CD4+ T-cell count threshold or an AIDS-defining symptom to qualify for treatment." (PMID 38784816, 2024). "This study describes the unexpected strong, negative association of spleen weight with CD4+ cell count in splenectomized patients with VL and AIDS and less expressive changes with CBC." (PMID 38491526, 2024). "Thus, caspase inhibition prevents in vivo the depletion of CD4+ T cells and delays the progression to AIDS." (PMID 38534416, 2024). "HIV infects cells of the immune system through interaction with CD4, CCR5, and CXCR4 and establishes long-lasting infections that develop into the acquired immunodeficiency syndrome if left untreated." (PMID 38557496, 2024). "The most advanced and late stage of HIV infection is acquired immunodeficiency syndrome (AIDS), marked by declining CD4+T lymphocytes numbers, increasing viremia levels, and greater susceptibility to potentially lethal opportunistic infections." (PMID 39476027, 2024). "The CD4/CD8 ratio is a crucial immunological parameter used in the context of HIV infection and AIDS (acquired immunodeficiency syndrome)." (PMID 38428854, 2024). "From HIV/AIDS patient with low CD4+with OC, the isolate ofCandidaspp." (PMID 38387624, 2024). "PLHIV on ART with a low CD4 count, high CD8+ T-cell levels, or a low CD4/CD8 ratio have been associated with poor prognosis, including residual viremia despite treatment and increased AIDS mortality." (PMID 38804398, 2024). "If the level CD4 count of a patient is low, then the ability of the immune system to fight against infections is compromised, leading to individuals being susceptible and transitioning from HIV to AIDS." (PMID 39058196, 2024). "Second, existing literature suggests that factors such as HIV/AIDS viral load, CD4+/CD8+ T cell ratio, and adherence to ART treatment may influence patients’ survival time and HIV/AIDS-related mortality." (PMID 38454987, 2024). "Based on their ages, CD4 counts, and comorbidities at presentation, one patient (1/10) was classified as having stage 1 HIV disease (low risk), while 9/10 patients were classified as having stage 3 disease (AIDS)." (PMID 38976031, 2024). "Similar results were found in both groups, except for a significantly higher proportion of coinfected patients exhibiting CD4+ T-cell counts less than 200 cells/μL, which could explain the increase in AIDS-related events recorded in this group." (PMID 38999501, 2024).
AIDS (continued). "For example, infection with HIV subtype D is associated with a rapid decrease in CD4+ cell count compared to subtype A1 and other non-D subtypes, resulting in faster progression to AIDS and earlier initiation of ART." (PMID 39399152, 2024). "In the AIDS data set, we focus on a single longitudinal covariate, the CD4 count z1i(t)." (PMID 39211944, 2024). "Among study participants who immigrated after the age of 15 years and acquired HIV after migration to France, 83/550 (15.1%) had a CD4+ T-cell count < 200/mm3, including 24/550 (4.4%) who had an acquired immunodeficiency syndrome (AIDS) defining event at entry into care." (PMID 38487889, 2024). "The profound immunosuppression (CD4+ count of 2 cells/μL) is indicative of advanced AIDS." (PMID 39233730, 2024). "The CD4/CD8 ratio is emerging as a potential biomarker for non–AIDS-related events." (PMID 37846087, 2024). "Predicting complications: A low CD4/CD8 ratio is associated with an increased risk of various HIV-related complications, including opportunistic infections and non-AIDS-related conditions such as cardiovascular disease, neurocognitive impairments, and certain cancers." (PMID 38428854, 2024). "This study proposes applying an induced smoothing method to the existing nonsmooth estimator to fit the semiparametric quantile residual life regression model for data with time-varying biomarkers that are repeatedly measured, such as CD4 cell counts in the Korea HIV/AIDS cohort study." (PMID 38368350, 2024). "Thus, HIV-1 infection and AIDS was, for a long time, considered a disease of the CD4+ T cell lineage." (PMID 38400063, 2024). "We present a 45-year-old African American male with a medical history of advanced-stage HIV/AIDS (CD4 count: 1 cell/μL) and poor adherence to highly active antiretroviral therapy (HAART), who presented with symptoms of diarrhea, weakness, and respiratory distress." (PMID 38864070, 2024). "Additionally, 154 individuals (10.8%) had a history of AIDS, with a median CD4 T cell nadir of 355 cells/μL." (PMID 39770774, 2024). "Human immunodeficiency virus (HIV) primarily attacks the immune system by targeting cluster of differentiation 4 (CD4) cells, and if not diagnosed early, it can progress to acquired immunodeficiency syndrome (AIDS), which is a severe immune deficiency." (PMID 39569255, 2024). "Furthermore, individuals infected with HIV-2 typically develop clinical AIDS at higher mean CD4 percentages than those infected with HIV-1." (PMID 39749085, 2024). "The CD4 count is an essential biomarker in HIV/AIDS management and research." (PMID 39687438, 2024). "However, in a study involving 466 patients with AIDS-related KS, fewer than half had KS diagnosis at a CD4 count < 200 cells/μL, 15% at a CD4 count ≥ 500 cells/μL, and 29% had suppressed HIV viral load (500 copies/ml)." (PMID 39156295, 2024). "The most often selected predictors for the development of an AIDS event after more than one year of continuous treatment were a low CD4 count and a previous AIDS-defining condition, which are both indicators of advanced HIV infections and an already substantially impaired immune response." (PMID 38381307, 2024). "However, instead of increasing T-lymphocyte proliferation, VL and AIDS comorbidity cleared the spleen of CD4+ cells that otherwise would be released for circulation." (PMID 38491526, 2024). "Although chimpanzees represent the closest genetic model and may be naturally HIV‐1 infected, they rarely develop AIDS with little CD4 decline and innately less impactful CD8 responses versus humans, meaning they are seldom used." (PMID 39319247, 2024). "A Cox multivariate analysis indicated that darunavir did not lead to a significantly higher risk of TF (aHR 1.18, 95% CI 0.79–1.77, p = 0.412) when compared to dolutegravir, after adjusting for AIDS-presenting, absolute CD4 count, CD4 percentage and CD4/CD8 ratio at baseline." (PMID 37243208, 2023).
AIDS (continued). "Similarly, the indirect effect going through Median CD4 was calculated as the product of coefficients from unfavorable S.E.E. to median CD4 (0.06) and from the median CD4 to AIDS-related mortality (-0.10)." (PMID 37159438, 2023). "Another study proposed a definition of advanced patients as patients who present with a CD4 count < 200 cells/μL and/or have an AIDS-defining event within a month after HIV diagnosis, or patients with a first-reported CD4 count < 350 cells/μL or an AIDS-defining event within a month after diagnosis." (PMID 36895684, 2023). "One possible explanation for this result is that the impact of HIV infection on both CD4+ cells and CD8+ cells is very weak before the acquired immunodeficiency syndrome starts to develop." (PMID 36674980, 2023). "while Cryptococcus is known to cause meningitis, encephalitis, and meningoencephalitis in immunocompromised patients, especially those with AIDS (CD4 <100), and found to be rapidly fatal, instances of ventricular involvement with chronic sequelae are exceedingly rare." (PMID 38106779, 2023). "Poor medication adherence, low CD4 count, type of ART regimen, duration of the disease since diagnosis, and social support are the other prevalent factors associated with poor sleep quality among people living with HIV/AIDS." (PMID 37359994, 2023). "Moreover, the log CD4 count of AIDS patients who has other disease is 5.04 more likely to be co-infection than who has no other disease, controlling other predictors as constant." (PMID 38974259, 2023). "The US President's Emergency Plan for AIDS Relief (PEPFAR) recommends CD4 testing for the identification of AHD in specific contexts (at the initiation of ART for PLHIV over 5 years, upon re‐initiation of care for those out of care for more than a year and for individuals with virologic failure)." (PMID 36880429, 2023). "The mean of CD4 cell for AIDS patients lived with TB is maximum at the eight-visiting time." (PMID 38974259, 2023). "Viral loads decreased more gradually during the observation period in men compared to women (higher in individuals between the ages of 13 and 19 compared to the older age group) and in HIV/AIDS patients with low CD4 counts compared to those with high CD4 counts." (PMID 37887742, 2023). "Indeed, 35% of migrant women and 45% of migrant men are diagnosed with advanced HIV disease (CD4 count below 200 cells/mL or AIDS-defining event), and migrants account for 46% of people diagnosed with AIDS." (PMID 37267406, 2023). "Altogether, the impact of AIDS phenotypic changes in CD4+ T cells on the pool of productively infected cells and their contribution to the late dissemination of HIV during advanced disease are currently unknown." (PMID 38420260, 2023). "The progressive loss of CD4+ T cells due to HIV infection leads to severe immunosuppression and a compromised immune response, the underlying cause of opportunistic infections and diseases associated with acquired immune deficiency syndrome (AIDS)." (PMID 37766242, 2023). "The persistence of a very low ratio (<0.3) predicted the risk of serious non-AIDS-related events or death, independent of CD4 count." (PMID 38131882, 2023). "We analyzed data from the CoRIS cohort to determine whether CD4 count, CD8 count, and CD4/CD8 ratio at year two of antiretroviral therapy (ART) could predict the risk of serious non-AIDS events (SNAEs) during the next five years." (PMID 37639938, 2023). "AIDS status, but not the duration of the disease or the last biological activity markers (CD4 count or viral load), was associated with prognosis." (PMID 36915207, 2023). "However, HIV specifically targets and infects CD4+ T cells, leading to a gradual depletion of this cell population and ultimately resulting in the onset of AIDS." (PMID 37408185, 2023). "The AIDS phase occurs when CD4 + T cell count is less than 200 cell/μl." (PMID 37020854, 2023). "Therapeutic intervention leads to recovery of the CD4+T cell count in HIV/AIDS patients." (PMID 36851577, 2023).
AIDS (continued). "The negative association of both AIDS and non-AIDS related morbidity and mortality with CD4 cell count levels at ART initiation is well established by many studies." (PMID 36996018, 2023). "While there is evidence of significant depletion of CD4 T cells in COVID-19 patients and CD4 cell deficiency is the most important driving factor for the development of PCP, as seen in AIDS, the incidence of PCP in COVID-19 appears to be far lower than that reported in AIDS." (PMID 37623583, 2023). "Moreover, the log CD4 count of AIDS patients who has other disease is 5.04 more likely to be infected with TB than who has no other disease, controlling other predictors as constant." (PMID 38974259, 2023). "CD4+ count has been proposed as a potential determinant of survival in combination with other clinical data such as sex, race, presence of comorbidities, clinical acquired immunodeficiency syndrome (AIDS), and age at HAART initiation." (PMID 36826348, 2023). "Higher levels of virus replication result in the rapid loss of CD4+ T lymphocytes, facilitate the emergence of drug-resistant HIV-1 quasispecies, and promote progression toward late-stage disease and acquired immunodeficiency syndrome (AIDS)." (PMID 36672628, 2023). "However, it is interesting to note that half of the patients had a CD4 T-cell nadir < 250/mm3, and 20% of them had an AIDS-related event in their history." (PMID 37108969, 2023). "Expected mean residence time in suboptimal and optimal viro‐immunological states and probability of residence or transition from one status to another, divided by sex, CD4+/CD8+ ratio, HIV RNA, history of AIDS‐defining events, presence of resistance‐associated mutations." (PMID 36840488, 2023). "The absence of association of the variant with the levels of CD4+ TL differs from the suggestion that the heterozygous Δ32 allele is associated with a slower progression to AIDS." (PMID 36902388, 2023). "However, malignancy and earlier AIDS-defining events were more common in PWH with CD4+T-cell count < 200 cells/μL (25% versus 5.8%, p = 0.006, and 33.3% versus 7.7%, p = 0.001, respectively)." (PMID 38004713, 2023). "However, 114/270 (42.2%) of patients had a nadir CD4 count < 200 cells/mm3, and among these, 72/114 (63.2%) had a prior diagnosis of AIDS." (PMID 38131882, 2023). "In addition to this, the low CD4 count, high AIDS rate, and a high prevalence of multiple co-morbidities among PLWH with COVID-19, seem to have a key role in the high COVID-19 mortality in a district hospital setting." (PMID 36855103, 2023). "Low CD4/CD8 ratios have been associated with T-cell activation, immune senescence, and higher morbidity and mortality, mainly related to the more frequent occurrence of non-AIDS events." (PMID 37112915, 2023). "Mitochondria alteration in CD4+ T cells from HIV-infected individuals (101, –, 104) and in SIV-infected RMs has been reported earlier and associated with a higher propensity of CD4+ T cells to die and to develop AIDS (3, –, 5)." (PMID 37656815, 2023). "HIV infects immune cells expressing the CD4 receptor, e.g., CD4+ T cells and DCs, which leads to a progressive degeneration of the immune system and eventually results in the onset of acquired immunodeficiency syndrome (AIDS)." (PMID 36839937, 2023). "Furthermore, they had a lower median current (605 vs. 710 cells/μl, respectively) and nadir CD4+ cell count (160 vs. 260 cells/μl, respectively) and a higher prevalence of prior history of AIDS (39 vs. 18%, respectively)." (PMID 37199566, 2023). "After CD4 cells were captured in the chamber, a photo was acquired through the mobile phone camera, and an application program was then activated to count the numbers of captured CD4 cells for AIDS diagnosis." (PMID 36906581, 2023).
AIDS (continued). "The significance of Cr-Ag screening has been clearly stated in the guidelines of the WHO and China, which suggest that serum and cerebrospinal fluid Cr-Ag screening should be enhanced in the late stage of AIDS, especially for CD4 + lymphocyte counts < 100 cells/μl." (PMID 37024795, 2023). "Similarly, Dominik Matthes has traced how patients with HIV/AIDS have navigated opting for traditional medicines in place of antiretrovirals while still routinely attending clinic to test their CD4 counts." (PMID 37289748, 2023). "Furthermore, complications and AIDS-defining sequelae, carcinomas, and infections arise from the reduction in the CD4 cell count and, thus, the destruction of the immune system." (PMID 36834069, 2023). "This might be because both of them are in the “AIDS” group and displayed the lowest CD4 counts of all participants." (PMID 38420260, 2023). "Role functioning indicates the influence of health status on work and school attendance and may be influenced by AIDS and CD4 counts." (PMID 36859482, 2023). "However, a high number of people living with HIV/AIDS (PLWHA) present themselves to the public health system (SUS) for the first time with a CD4 count below 200 cells/mm3." (PMID 37896874, 2023). "However, some of the patients were diagnosed in advanced stages of HIV, with low CD4 T-cell counts at diagnosis, and a history of AIDS-defining illnesses, including neoplastic diseases." (PMID 37242997, 2023). "Patients with HIV/AIDS having a CD4 count of less than 240 are put on life prolonging ARV drugs." (PMID 38357124, 2023). "Participants in Atlanta had had HIV and been on ART for a longer duration, had lower recent CD4 counts, were more likely to report having been diagnosed with AIDS and were less likely to have undetectable viral load, despite being more likely to take only one HIV pill per day." (PMID 37439051, 2023). "Although the U.S. Center for Disease Control’s definition of Stage 3 AIDS in human patients (<200 CD4 lymphocytes/μL blood; CDC.gov) is satisfied in FIV progressor cats, these cats nevertheless enter a prolonged asymptomatic phase featuring minimal to no clinical morbidity." (PMID 37632117, 2023). "A lower CD4 count often results in an AIDS-defining illness and increased mortality." (PMID 37908331, 2023). "The predictive ability of CD4/CD8 was maintained even in individuals with CD4 count >500 cells/μL, in whom CD4 no longer predicted an increased risk of non-AIDS events." (PMID 37639938, 2023). "Since plasma viral load remains high in AIDS individuals, we can hypothesize that these highly differentiated CD4+ T cells are responsible for HIV production in peripheral blood in the terminal stage." (PMID 38420260, 2023). "In addition, having a current CD4+ cell count below 200 cells/μl, a last measured HIV viral load of more than 200 copies/ml, and a history of prior AIDS were each also independently associated with a higher odds of hospitalization." (PMID 37199566, 2023). "In addition to the decline in CD4+ T-cell immunity caused by HIV infection, a decreased CD4:CD8 ratio has also shown its potential as a predictive biomarker for non-AIDS-defining cancer risk within large HIV study cohorts." (PMID 38201498, 2023). "In addition, we recommend researchers to further investigate the effect of CD4 count for MSDs among HIV/AIDS patients following ART." (PMID 37596525, 2023). "Here the authors assess the impact of experimental CD4+ T cell depletion in AGM and show that lack of disease progression and resistance to AIDS in this model are independent of CD4+ T cell loss." (PMID 36813761, 2023). "CD4+ T-lymphocyte (CD4) counts have been found to be one of the strongest predictors of immunological recovery and disease progression after initiating ART among people living with HIV (PLWH); the majority of AIDS-related deaths occur in patients with CD4 count less than 350 cells/μL." (PMID 38124745, 2023).